STAT3 (signal transducer and activator of transcription 3)
Diseases named in the same sentence as STAT3 in open-access papers (continued):
Sharing a sentence is not in itself a finding about the gene and the disease.
cancer (continued). "It has been reported that Stat3 constitutive activation and nuclear localization are associated with NPC cell growth, cancer stem-like characteristics and metastasis, and activated Stat3 is a target for anti-NPC drug discovery." (PMID 25915430, 2015). "Here we show that genetic inactivation of Stat3 or IL-6 signalling in a Pten-deficient PCa mouse model accelerates cancer progression leading to metastasis." (PMID 26198641, 2015). "Constitutive STAT-3 activation is associated with various human cancers and commonly suggests poor prognosis." (PMID 26418031, 2015). "On the other hand, resveratrol possesses multifaceted targeting capacities and the cancer-associated signaling pathways mediated by STAT3, Wnt2 and/or Notch1/2 have been known as its molecular targets." (PMID 25896424, 2015). "Many researches confirm STAT3 as a causal role in oncogenesis, and provide validation of STAT3 as an oncotarget for cancer drug discovery." (PMID 25915156, 2015). "In this study, we show that loss of IL-6/Stat3 signalling in a Pten-deficient PCa model accelerates cancer progression leading to metastasis." (PMID 26198641, 2015). "Granzyme M induced the epithelial-mesenchymal transition (EMT) in cancer cells associated with STAT3 activation." (PMID 25788270, 2015). "STAT3 has many biological functions in normal cells and, like other oncogenes, is insufficient on its own to cause cancer." (PMID 25784959, 2015). "For instance, the paracrine sources of IL-6 from cancer-associated fibroblasts, adipocytes, or myeloid cells on the edge of the tumors and the autocrine production of IL-6 can both activate the STAT3." (PMID 26631279, 2015). "There are evidences that signal transducer and activator of transcription protein 3 (STAT3) is implicated in the development and progression of cancer and plays a role in inducing neoplastic transformation." (PMID 26186918, 2015). "S1PR1, one of the common targets of miR-148a-3p, -148b-3p and -363-3p, is implicated in NFκB/IL-6/STAT3/S1PR1 amplification loop that is important for chronic colitis-related cancer and can be suggested as therapeutic option." (PMID 26692821, 2015). "Both in vivo and in vitro studies have identified SGPP1 and Smad2 as two novel targets of miR-27a, which is linked to STAT3 to regulate cancer cell proliferation, apoptosis and migration." (PMID 25166914, 2014). "This supports the notion that HER2/ER overexpression activates STAT3 which leads to an increase in cancer stem cell markers, causing overexpression of HER2 and cells become resistant to chemotherapy." (PMID 24297508, 2014). "EGFR, JAK tyrosine kinase, Src tyrosine kinase and Erk1/2 play a dominant role in STAT3 phosphorylation and are linked with cancer cell proliferation, metabolic regulation and metastasis." (PMID 24799285, 2014). "Experimental results have revealed that loss of SOCS3 indeed contributes to the activation of STAT3 in cancer cells, thereby promoting their proliferation, survival and motility." (PMID 24995504, 2014). "Of the seven Signal Transducer and Activator of Transcription (STAT) family members, STAT3 has been most consistently implicated in a range of common cancers in humans, including; lung, breast, ovarian, prostate, and colon." (PMID 24804649, 2014). "Studies in cancer cell lines linked its anti-angiogenic potential to the decreased HIF-1 or STAT-3 signaling and resultant down-regulation of pro-angiogenic VEGF." (PMID 25526033, 2014). "Clinical, epidemiological and molecular studies support a strong association between inflammation and cancer, as well as between STAT3 and inflammation." (PMID 25026286, 2014). "Constitutive activation of STAT3 is strongly associated with cancer development and commonly suggests a poor prognosis." (PMID 25266147, 2014). "Constitutive activation of STAT3 has been reported in many human cancer cell lines and primary tumors, and this activation is associated with poor outcomes of a number of cancers." (PMID 24662938, 2014).
cancer (continued). "This facet of STAT3 biology likely contributes to the association of STAT3 with metastasis and a poor prognosis in multiple cancer types." (PMID 24743777, 2014). "STAT3 is rarely mutated in cancer cells but rather activated by upstream signals, such as receptor tyrosine kinses (RTKs), mutated JAKs, or oncogenic cellular tyrosine kinases (CTKs), such as Src." (PMID 24995503, 2014). "Tumorigenic STAT3 activation has been frequently linked to more malignant cancer behaviors, including growth, epithelial-mesenchymal transition, migration, invasion and metastasis." (PMID 24743777, 2014). "Gain-of-function mutations involving JAKs have been implicated in activating STAT3 in specific types of cancer." (PMID 24995504, 2014). "This review describes potential interactions of STAT3 with other cancer-associated pathways and molecular mechanisms that modulate therapeutic efficacies of STAT3 inhibitors." (PMID 24662938, 2014). "In the last decade, several anti-STAT3 small molecule inhibitors have shown promising potential by counteracting cancer cell-associated proliferation, inflammation, and importantly chemoresistance." (PMID 24782986, 2014). "STAT3, which was initially identified as a mediator of the inflammation-associated acute phase response, has been of particular interest in cancer biology." (PMID 24762632, 2014). "Signal transducer and activator of transcription-3 (STAT3) is a potential target for treating NF1-associated or NF1-deficient cancers, as STAT3 is activated downstream in the PI3K/mTOR pathway." (PMID 25026295, 2014). "Despite the known association of STAT3 phosphorylation with cancer, the mechanisms that regulate STAT3 are not well understood." (PMID 25417721, 2014). "The homeostasis of STAT3 phosphorylation and activation is frequently disrupted in cancer cells due to the loss of SOCS expression." (PMID 24995504, 2014). "We found that STAT3 signaling is also activated in EJ TCC cells and short term in vitro and in vivo resveratrol treatments can inhibit STAT3 activation and down-regulate the expression of STAT3 and its downstream cancer-associated genes." (PMID 24587049, 2014). "As STAT3 is mutated in different cancer types, it is worth testing if SH003 is able to target those types of cancer cells." (PMID 24976685, 2014). "Stat3 is associated with cell proliferation and survival and it is crucial in the prognosis of many cancers and a potential target for anticancer therapy." (PMID 25057499, 2014). "In fact, the STAT3 inhibitors developed in our laboratory drastically induced ROS generation in the susceptible cancer cells." (PMID 24662938, 2014). "Of the 7 known STAT proteins, activated STAT3 is reported to be strongly associated with various cancers including OvCa." (PMID 24887420, 2014). "Signal transducer and activator of transcription 3 (STAT3) is an important transcriptional factor frequently associated with the proliferation and survival of a large number of distinct cancer types." (PMID 25417721, 2014). "Signal Transducer and Activator of Transcription-3 (STAT3) is often constitutively activated in cancer cells and is a causative agent in the transformation to a cancerous phenotype." (PMID 23434903, 2013). "The STAT3 signal pathway has been linked to cancer, and it triggers critical target genes regulating cell proliferation and survival." (PMID 24386318, 2013). "The antiproliferative effect of I3MO, a derivate of the naturally occurring compound indirubin used in traditional Chinese medicine against cancer, was linked with the selective inhibition of signal transducer and activator of transcription 3 (STAT3)." (PMID 24165129, 2013). "Alternatively, the STAT3 pathway has been shown to be constitutively activated in many human cancers and has been implicated in oncogenic transformation and progression." (PMID 24274066, 2013).
cancer (continued). "As STAT3 activation in cancer cells is known to cause resistance to chemotherapy and radiotherapy, STAT3 inhibition is considered to be effective for patients with advanced malignant tumors." (PMID 24260055, 2013). "NF-κB and STAT3 are important transcription factors involved in mediating inflammatory and immune responses, and have also been linked to many cancers, including GBM." (PMID 24244348, 2013). "IL-6 is a major activator of STAT3 signaling and it is associated with poor prognosis in different cancers." (PMID 24146823, 2013). "Mouse studies demonstrated that IL-6 is important for both tumor development and growth in colitis associated cancer, with IL-6 promoting both proliferation and survival of intestinal epithelial cells via the activation of the transcription factor STAT3." (PMID 23987103, 2013). "Increased IL-6 in LNCaP-IL-6+ cancer cells showed a growth advantage, STAT3 activation, high expression of VEGF association with androgen-independent growth." (PMID 23806095, 2013). "Dysregulated STAT3 signaling is linked to chronic inflammation and cancer and to the connection between these two diseases." (PMID 24192293, 2013). "STAT3 regulates a wide range of genes associated with cancer cell invasion and metastasis, and MMPs is a family of the critical STAT3 target genes." (PMID 23326564, 2013). "In numerous types of malignant tumors, STAT3 activation in cancer cells is associated with a poor clinical prognosis or higher grade histological malignancies." (PMID 24260055, 2013). "Constitutively active STAT3, caused by upstream dysregulation, is found in a large number of human cancers and is generally associated with a poorer prognosis." (PMID 24142927, 2013). "The transcription factor, signal transducer and activator of transcription 3 (Stat3), has been implicated in the growth and progression of several cancer types including prostate." (PMID 22454635, 2012). "Recent studies have also linked the activation of STAT3 pathway to high histologic grade and advanced stage in several cancers." (PMID 22662257, 2012). "Selectively targeting activated STAT3 signaling has been shown to be effective in inhibiting cancer-associated processes and cancer cell viability." (PMID 23056374, 2012). "Several IL-6 signaling pathway-related genes including STAT3 are also associated with migration and invasion of cancer cells." (PMID 22745766, 2012). "STAT3 is constitutively activated in nearly all human cancers and it is associated with various transcriptional activities in the nuclei." (PMID 22937006, 2012). "Overexpression and activity of Stat3 has been linked to the invasion and metastasis of several cancers in humans, including cutaneous squamous cell carcinoma (SCC), colorectal adenocarcinoma, and melanoma." (PMID 21595927, 2011). "Recently, inhibition of Janus kinase 2 (JAK2)/signal transducer and activator of transcription 3 (STAT3) signaling was shown to underlie the effects of Cuc family on inducing cell death in cancer." (PMID 21304528, 2011). "Constitutive expression and activation of STAT-3, a common oncogenic signaling pathway, has been clearly associated with cancer progression and poor prognosis." (PMID 21875439, 2011). "Our results, along with the study in other different types of cancer, indicate the existence of an association between STAT3 activation in monocytes and poor prognosis." (PMID 22136659, 2011). "It has been suggested that the inhibition of JAK2/STAT3 underlies the apoptosis when cancer cells are treated with Cuc." (PMID 21304528, 2011). "Constitutive activation of STAT3 has been implicated in the tumorigenesis of many cancers both inside and outside of the CNS and has been shown to be sufficient to transform cells to a malignant phenotype in vitro." (PMID 22190972, 2011).
cancer (continued). "Discovery of T cell populations producing IL-17 (Th17) and their association with STAT3 expression in human cancers have recently generated an interest in defining the role of these cells in GBM pathogenesis." (PMID 22190972, 2011). "For instance, epigenetic silencing of the negative regulator SOCS3 occurs in epithelial cancers, while other cancers show somatic mutations in Stat3-inactivating phosphatases T and δ." (PMID 20478049, 2010). "By contrast, Stat3 mediates activity of cytokines generally associated with systemic acute phase and cancer-promoting inflammatory responses." (PMID 20478049, 2010). "Because Stat3 activation was positively associated with proliferation potential in cancer cells, we measured the absorbance of the SW1990 cell line in the presence of AG490." (PMID 20482858, 2010). "STAT3 activation has been associated with cell survival, proliferation, and invasion in various human cancers." (PMID 22069560, 2010). "Among them, STAT3 is often constitutively phosphorylated (p-STAT3) in human cancers and implicated in tumorigenesis." (PMID 22312393, 2010). "Accordingly, aberrant and persistent Stat3 activation is a frequent observation in human cancers of epithelial origin and is often associated with poor outcome." (PMID 20478049, 2010). "Stat3 can also be activated by other cancer-associated receptor tyrosine kinases, including those for epidermal growth factor and scatter factor c-Met." (PMID 20478049, 2010). "Although the reasons for aberrant STAT3 activity in cervical precancer and cancer lesions remains to be investigated, its association with HPV16 infection in cervical carcinogenesis is evident from data presented in the present study." (PMID 20977777, 2010). "Several STATs have been associated with the induction and survival of cancer cells, however, STAT3 is especially prominent in this regard." (PMID 19127268, 2009). "Constitutive STAT3 activation has been linked to cancer initiation, proliferation, promotion of angiogenesis and inhibition of apoptosis." (PMID 19127268, 2009). "Suppressing STAT3 signaling pathway causes growth inhibition and apoptosis of cancer cells, therefore STAT3 represents a validated target for cancer therapy." (PMID 19744341, 2009). "The activation of signal transducer and activator of transcription 3 (Stat3) has been implicated in the oncogenesis of cancer and is regarded as a novel target for cancer therapy." (PMID 17311011, 2007). "The increased activation of Src and Signal Transducer and Activator of Transcription 3 (Stat3) proteins is associated with breast tumorigenesis as well as a number of other human cancers." (PMID 17967179, 2007). "In head and neck squamous cell carcinoma (SCC), there is evidence that Stat3 constitutive activation is linked to cancer development and growth." (PMID 15316561, 2004). "Importantly, "Tr1 skewing" is evident in both mouse T cells expressing cancer-associated STAT3 variants and humans afflicted with T-cell malignancies." (PMID 42164506, 2026). "In addition, NME4 regulates PD‐L1 expression through the STAT3 signaling pathway, which is associated with immune evasion in aggressive cancers." (PMID 41584726, 2026). "To causally determine whether TM4SF1 palmitoylation is required for the palmitate-induced phosphorylation of STAT3, we overexpressed wildtype and palmitoylation mutated (C79A+C88A) Tm4sf1 in 4T1 cancer cells silenced for wildtype Tm4sf1." (PMID 41826695, 2026). "STAT3 has been associated with pro-tumorigenic activities in many cancers." (PMID 40426911, 2025). "Additionally, STAT3 is critical for the maintenance of cancer stem cells (CSCs), which are implicated in cancer recurrence and metastasis." (PMID 40075607, 2025).
cancer (continued). "The roles of NF-κB and STAT3 pathways in tumor formation are widespread across many tissue types and strongly associated with inflammation in cancers of the stomach, colon, liver, lung, and pancreas, influencing cell proliferation, survival, angiogenesis, and immune evasion." (PMID 40732979, 2025). "STAT3 is frequently hyperactivated and associated with poor clinical prognosis in the majority of human cancers, making it an important potential therapeutic target for cancer treatment 19,20." (PMID 40303303, 2025). "Notably, alantolactone, atractylenolide I, imperatorin, ursolic acid, and brassinin have further emphasized the therapeutic potential of targeting STAT3 to prevent fat loss in cancer cachexia." (PMID 40704145, 2025). "Additionally, cancer-derived interleukin-6 (IL-6) activates KDM2A in cancer-associated fibroblasts via the STAT3/NF-κB p50 pathway, promoting stromal-mediated resistance." (PMID 40941035, 2025). "In addition, STAT3 has been widely identified by numerous studies as a carcinogenic transcription factor that causes malignant transformation, so STAT3 has been considered an attractive target for the treatment of cancer." (PMID 40078291, 2025). "Pentacyclic triterpenoids such as ursolic acid, celastrol, and betulinic acid have been shown to modulate the JAK/STAT3 signaling pathway, which may underlie their anti-inflammatory, anti-cancer, and cardioprotective effects." (PMID 41373772, 2025). "Genetic/epigenetic alterations underlie aberrant STAT3 signaling in cancer cells." (PMID 41104968, 2025). "Additionally, while HF exerts protection via SIX4/AKT/STAT3 activation, this pathway is also implicated in promoting tumor progression across various cancer types." (PMID 41511301, 2025). "Persistent and aberrant activation of STAT3 is associated with inflammation and cancer development." (PMID 40303303, 2025). "Furthermore, excessive STAT3 activation in cancer models exacerbates weight and muscle mass loss compared with controls." (PMID 39764565, 2025). "The IL-6/STAT3 signaling pathway is critical for cancer cachexia-induced muscle loss." (PMID 40869331, 2025). "STAT3 signaling is hyperactive in many human cancers and associated with a worse prognosis." (PMID 40606688, 2025). "Persistent activation of STAT3 has been reported in a variety of cancer types, and a poor prognosis of cancer may be associated with the phosphorylation level of STAT3." (PMID 40943427, 2025). "Upon binding to their respective receptor complexes, all IL-20 subfamily members initiate activation of the Janus kinase (JAK) and STAT pathway, with a particular emphasis on STAT3, aberrantly hyperactivated in many types of cancer and generally associated with a poor clinical prognosis." (PMID 40806452, 2025). "STAT3 has also been associated with poor responses to cancer therapy." (PMID 41009413, 2025). "STAT3 is broadly implicated in human disease, the most notable being cancer." (PMID 41115066, 2025). "STAT3 activation is associated with acquired drug resistance in cancer cells." (PMID 40149331, 2025). "In cancer stem cells (CSCs), STAT3 gain-of-function mutations or persistent activation further amplify these effects by promoting the expression of stemness-related transcription factors such as NANOG, SOX2, and OCT4, which are critical for maintaining the CSC phenotype." (PMID 40140827, 2025). "STAT3 hyperactivation could be caused by many factors, including cytokine production by cancer and immune cells, activation of oncogenes, and inactivation of tumor suppressor proteins." (PMID 39985075, 2025).